CTLA4 (cytotoxic T-lymphocyte associated protein 4)
Diseases named in the same sentence as CTLA4 in open-access papers (continued):
Sharing a sentence is not in itself a finding about the gene and the disease.
tumor (continued). "Building on these advances in DC vaccination, the response to anti-CTLA-4 blockade in poorly immunogenic tumours is contingent on DC activation, which was previously accomplished through GM-CSF vaccination, mimicking a typical ‘hot’ tumour state." (PMID 37454231, 2023). "Therefore, combining opaganib with anti-CTLA-4 also provides significantly improved antitumor activity in the LLC tumor model and increases survival longer than does either agent alone." (PMID 38069222, 2023). "By targeting both CTLA-4 and PD-1, these bispecific antibodies can simultaneously promote activation and proliferation of T cells, reduce regulatory T cell function, and enhance the killing of tumor cells by cytotoxic T lymphocytes." (PMID 37441075, 2023). "Moreover, in subsequent exposure to tumor cells, animals that had been given anti-CTLA-4 treatment were able to quickly eradicate the cancerous cells by means of the immune system." (PMID 37441075, 2023). "Thus, by irradiating the drainage lymph nodes of the tumor at 18 Gy, the effect of anti-CTLA-4 was abolished." (PMID 37539054, 2023). "Subsequently, we explored the use of ICB namely, single agent anti-PD-1 and anti-CTLA-4 therapy to determine if these agents might enhance anti-tumour Th1 immunity post-operatively using our ex vivo PBMC expansion protocol." (PMID 37359545, 2023). "Herein, using a CTLA4 blocker, we have demonstrated superior tumor inhibition with minimal irAE." (PMID 37259163, 2023). "Consistent with our previous work, mice treated with PancVAX delivered in combination with a STING agonist ADU-S100 and dual ICIs, anti–PD-1 and anti–CTLA-4 antibodies, displayed a significant improvement in the control of early tumor growth compared with vaccine alone or ICIs alone." (PMID 38063199, 2023). "When tumors had reached an average volume of 40 mm3 (4×107 number of cells), mice were treated with carrier fluid treatment (mock; control) or injected with 2×106 viruses (OV) in the tumor, or injected with viral particles together with anti-CTLA-4 (OV-aCTLA-4) for 5 consecutive days." (PMID 36766849, 2023). "Hence, along with expression of programmed death-1 ligand (PD-L1) on tumor cells, expression of CTLA-4 in the tumor microenvironment and its correlation with serum sCTLA- holds immense therapeutic potential." (PMID 36879122, 2023). "Besides, IFNG was also a key mediator of antitumor immunity with angiostatic activity, mediated the effects of anti-CTLA4 therapy on vessel perfusion and tumor growth." (PMID 36756126, 2023). "Thus, therapeutic strategies that block checkpoint inhibitors of the PD-1/PD-L1 and CTLA-4 pathways can promote tumour-reactive T-cell aggregation, thereby improving the antitumour response." (PMID 36860314, 2023). "MC38 tumor–bearing animals treated with mANK-101 or systemic PD-1 blockade alone each had a tumor-free survival rate of 40%, whereas the combination of ANK-101 and CTLA-4 blockade had tumor-free survival rates of 70% and 80% with concurrent or sequential therapy, respectively (data not shown)." (PMID 38063196, 2023). "The Fc-mediated effector mechanism of anti-CTLA-4 IgG1 can improve the priming of the T-cell response and increase the diversity of T-cell clones, which may help to bring new T cells to the tumor microenvironment." (PMID 37158938, 2023). "PD-1 and CTLA-4 blockade prevent T-cell suppression, thus potentiating the anti-tumor response." (PMID 37762046, 2023). "Although immune checkpoint blockade in AML has not proven beneficial, there may still be additional effects in combining CAR T cells and immune checkpoint blockage (PD-1, CTLA-4, etc.)that will improve T cell persistence and anti-tumor efficacy." (PMID 37345050, 2023). "It is hypothesized that the inhibition of CTLA-4 can prevent anergy during the priming stage of T-cell activation, allowing for increased infiltration of lymphocytes into the tumor." (PMID 38201559, 2023).
tumor (continued). "Anti-tumor efficacy was significantly enhanced when used in combination with other immunotherapies, including the recovery of immune responses in models with incomplete responses to anti-PD-L1 or anti-CTLA-4 monotherapy." (PMID 37834375, 2023). "If tumor resistance is developed under mAb therapy against CLTA4 or PD-1, it could mean that the tumor cells have changed their configuration of PD-1 or CTLA4." (PMID 36661747, 2023). "In addition, intratumourally injected engineered viruses showed anti-tumour effects against paediatric tumour models that are resistant to anti-CTLA-4 and anti-PDL1 antibodies." (PMID 37301780, 2023). "However, tumour cells are able to counteract the activity of PD-1 and CTLA-4 ICBs and can commission additional inhibitory pathways via expression of other ICs/ligands within the TME." (PMID 36445478, 2023). "This study showed that systemic propionate and butyrate limit anti-tumor attributes of anti CTLA-4." (PMID 37627114, 2023). "These new findings suggest that CTLA-4 and PD-1 may serve as novel target for the future in different tumor therapy." (PMID 37936703, 2023). "Immune checkpoint inhibitors (ICI) targeting programmed death 1 (PD-1), its ligand (PD-L1), or cytotoxic T-lymphocyte antigen 4 (CTLA-4) have shown promising results against multiple cancers, where they reactivate exhausted T cells primed to eliminate tumor cells." (PMID 36615128, 2022). "However, tumor cells are known to have immune escape mechanisms including PD-1/PD-L1 and CTLA4 pathways." (PMID 35711837, 2022). "It has been shown that tumour cells may escape from the immune surveillance by activating the CTLA-4B7 (B7 being the ligand of CTLA-4) and PD-1/PDL-1 checkpoint signalling pathways, which in turn suppress the CD8+ cytotoxic T-cell immune response." (PMID 35204486, 2022). "We also assessed tumor mutational burden (TMB), microsatellite instability (MSI), cancer stem cell (CSC) index, sensitivity of antineoplastic drugs, efficacy of anti-PD-1 and anti-CTLA4 immunotherapy between high and low m7GRG_Score groups." (PMID 36300121, 2022). "Among ICIs, PD-1 and CTLA-4 inhibitors are the most effective for tumor immunotherapy." (PMID 36110551, 2022). "Previous studies revealed that CTLA4 is constitutively expressed on tumor cells, and, therefore, CTLA4 blockade might stimulate tumor cell apoptosis and lead to the regression of tumors." (PMID 36159789, 2022). "In this study, we also conducted correlational analysis for the two subtypes and the expression of tumor immune checkpoint genes (PD-1, PD-L1, CTLA-4, and HAVCR2), and our results revealed that subtype A was positively associated with the expression of PD-L1, HAVCR2, and CTLA-4." (PMID 35350786, 2022). "CTLA-4 is a negative regulator of T cells primarily acting within lymphoid tissues, while the PD-1/PD-L1 system is mainly active in tissues where the immune response is on-going, including tumours." (PMID 35207291, 2022). "Thus, targeting CD73 becomes a novel method to improve anti-tumor immunity by combining to anti-CTLA-4, anti-PD-1 or anti-CD137 Abs." (PMID 35711418, 2022). "Monoclonal antibodies against CTLA-4, PD-1/PD-L1 are designed to reinvigorate exhausted T cells and restore immune-mediated elimination of malignant cells, a strategy that has highly successful against multiple tumor subtypes including NSCLC." (PMID 35992832, 2022). "Whilst CTLA4 suppressive function will be blocked other Treg suppressive mechanisms may still function, potentially affecting outcomes in anti-tumour immunity." (PMID 36119113, 2022). "EXO-OVA-mAb presented stronger ability of activating T cells than others and increased the CTLs/Treg ratio within the tumor site, and this phenomenon may be attributed to the crucial role of anti-CTLA-4 antibody." (PMID 36733388, 2022).
tumor (continued). "Similarly, a synergistic effect of the triple combination of vorinostat (HDACI) with anti-CTLA-4 and anti-PD-1 was observed in a triple-negative 4T1 breast cancer mouse model through boosting the anti-tumor activity." (PMID 35897717, 2022). "However, in tumors, immune checkpoints, such as programmed cell death 1 (PD-1) and cytotoxic T lymphocyte antigen 4 (CTLA-4), are abnormally activated, resulting in a weakened tumor immune response." (PMID 36238278, 2022). "Notably, cotreatment with PF543 and CTLA-4 mAb further restrained tumor growth compared with that obtained with PF543 or CTLA-4 mAb treatment alone." (PMID 36050478, 2022). "While tumor immunotherapy has been highly anticipated by researchers worldwide in recent decades, the discovery of tumor checkpoints in particular, including PD-L1, CTLA-4, CD47, and the Siglec family, is a landmark advance in tumor immunotherapy." (PMID 35733919, 2022). "Meanwhile, ICIs targeting cytotoxic T-lymphocyte associated protein 4 (CTLA-4), such as ipilimumab, and programmed death-1 (PD-1), such as nivolumab or pembrolizumab, alone or in combination can result in sustained tumor regression with the possibility of prolonged survival." (PMID 36290885, 2022). "Tumour‐infiltrating Tregs inhibit anti‐tumour immune response via several pathways, including the production of immunosuppressive cytokines, PD‐1 checkpoint inhibition and up‐regulation membrane protein PD‐1 and CTLA‐4,58, 59 ultimately facilitating tumour metastasis." (PMID 35969010, 2022). "Moreover, cdGMP combined with anti-CTLA-4/PD-1, and dithio-cdGMP combined with anti-PD-L1 have been verified to enhance the anti-tumor effect of ICB therapy." (PMID 35844623, 2022). "Combinations of anti-PD-1/PD-L1 and anti-CTLA-4 may have complementary action, resulting in better tumor response." (PMID 35631632, 2022). "In order to determine the prevalence of CTLA-4+ lymphocytes in a broad range of different tumor entities, a set of preexisting tissue microarrays (TMAs) was analyzed that included >4000 tumor samples from 90 types and subtypes as well as 76 different normal tissue categories." (PMID 35091676, 2022). "However, there was an inverse relationship for the expression of CTLA4 in tumor cells, where higher expression was correlated with lower BCRF survival." (PMID 36230846, 2022). "In addition, we determined the tumor inhibitory potential of P407-based anti-CTLA-4 and/or anti-PD-L1 therapy combined with PDT in MC38 and CT26 tumor-bearing mice models." (PMID 35974207, 2022). "The CTLA-4 antibody drug ipilimumab, which has been listed, can produce strong anti-tumour effects in vivo, but antibody drugs are expensive and have strong immunogenic effect, while CTLA-4 activation antibody to the systemic immune system will cause irAEs in a variety of peripheral tissues." (PMID 36195696, 2022). "The expression of PD-L1, CTLA4, TIM-3, and CD96 was significantly higher in high-risk populations than in low-risk populations, indicating that GILncSig expression was related to a high tumor immune resistance." (PMID 35571034, 2022). "Moreover, the frequency of tumour-infiltrating CD3+CTLA-4+, CD8+PD-L2+, CD8+TIGIT+, CD8+A2aR+ cells positively correlated with lymphovascular invasion (p = 0.03, p = 0.03 and p = 0.03)." (PMID 35366537, 2022). "Finally, we show that in advanced tumors, addition of cisplatin to anti CTLA-4 + anti PD-1 can extend mice survival and invigorate the decaying anti-tumor response." (PMID 36685577, 2022). "One hypothesis is that the different sensitivities might be driven by differences in expression of FcγRs and/or the presence of macrophages and NK cells or the presence of high surface CTLA-4 expressing Tregs in these tumor models." (PMID 35237846, 2022). "Also, despite the different clinical efficacy in cervical cancer carcinoma, inhibition of PD-1/PD-L1 or CTLA-4 signaling pathways is being studied alone or in combination with strategies such as chemotherapy and localized into the tumor." (PMID 36276117, 2022).
tumor (continued). "CTLA-4 is an important negative regulator of T-cell responses and a key molecular target for Treg inhibition in physiological and pathological immune responses, including autoimmunity, allergy, and tumor immunity." (PMID 35371055, 2022). "We hypothesized that the induction of tumor inflammation with the treatment of AS1411-SMG1-AsiC creates the optimal conditions to sensitize the tumor to the action of ICB agents such as anti-CTLA-4/PD-1 antibodies." (PMID 35991316, 2022). "The capacity of cytotoxic T lymphocytes (CTL) to eliminate tumor cells is the basis for the development of important tumor immunotherapies such as immune checkpoint inhibitors (e.g., anti-CTLA-4, anti-PD1, or anti-PD-L1 mAbs) and the development of cellular therapies such as CAR T cells." (PMID 35661707, 2022). "They found that CTLA-4 blockade reduced tumor competition for glucose, which may make treatment easier, encouraging its use in conjunction with tumor glycolysis inhibitors." (PMID 36009853, 2022). "Moreover, female metastases were enriched in CTLA-4+ T cells, intra-tumoral Treg lymphocytes and tumor cells expressing HLA class I, as compared to males." (PMID 36123711, 2022). "Moreover, anti-CTLA-4 therapy induced tumor regression and promoted survival after insufficient radiofrequency ablation (RFA) in the murine HCC model." (PMID 35392976, 2022). "Overall, high frequency of tumor-infiltrating FoxP3−Helios− T cells, and high frequencies of circulating FoxP3+, Helios+, FoxP3+Helios+, FoxP3+Helios−PD-1+, FoxP3+Helios+CTLA-4+, FoxP3+Helios−CTLA-4+ Tregs, and FoxP3−Helios+CTLA-4+ T cells, are associated with shorter DFS." (PMID 35655158, 2022). "In summary, the study indicated that the intratumoral fibrosis level was negatively correlated with the expression of CTLA4 in the tumor immune microenvironment of ccRCC, demonstrating the potential value of SHG in evaluating the immune invasion typing of ccRCC." (PMID 35710350, 2022). "It is important to note that, in the LS cohort, following anti-CTLA4 mAb therapy, compared to the isotype control, while the frequency of tumor infiltrating inflammatory CD4+T cells was high, there was no significant increase in the inflammatory phenotype in the lung and peripheral circulation." (PMID 35741331, 2022). "Exhausted T cells express immune checkpoint receptors, including programmed death-1 (PD-1), cytotoxic T-lymphocyte-associated antigen 4 (CTLA4), LAG-3, or T cell immunoglobulin and ITIM domain (TIGIT) that interact with their ligands PD-L1, CD80/CD86, MHC-II, and CD155, respectively, on tumor cells." (PMID 35954459, 2022). "YST-OVH therapy could potentiate anti-CTLA-4 therapy by promoting tumor antigen processing and presentation and T cell activation more potently than OVH therapy." (PMID 35688558, 2022). "Beyond the PD-1/PD-L1 and CTLA-4 pathways, an increasing number of preclinical and clinical immunooncology studies explore the merits of additional checkpoint targets to mount broad anti-tumor immunity and mitigate treatment resistance." (PMID 36389687, 2022). "They suggested that CTLA-4 blockade could induce tumor immunity either by ameliorating effector T-cell activities or by depletion of Treg." (PMID 35392976, 2022). "High co-overexpression of CTLA-4, PD-L1, and ICOS in normal lung (28 of 120 patients) was also significantly associated with decreased DFS (P = .0013), suggesting an immune tolerance to tumor neoantigens in some patients." (PMID 36108261, 2022). "Furthermore, a strong positive correlation was found between levels of FoxP3+Helios+ Tregs and CD4+CTLA-4+ T cells (r = 0.695, p = 0.0007) in tumor tissues." (PMID 35455287, 2022). "Previous studies have shown that iNOS expression is required for T cell recruitment by TAMs after low-radiation therapy, while anti–PD-1/CTLA-4 therapy induces a marked increase of intratumoral iNOS+ macrophages, coinciding with the arrival in the tumor of neoantigen-specific T cells." (PMID 35179953, 2022).
tumor (continued). "PD1/PD-L1 and CTLA-4 are important immune checkpoints that are responsible for tumor immune escape." (PMID 36092901, 2022). "The inhibition of these receptors led to the development of multiple immunotherapy bioengineered agents, some of which block PD-1 and CTLA-4 on T cells and others of which block the PD-1 ligand PD-L1 on tumor cells leading the immune system to recognize cancer cells and destroy them." (PMID 35409161, 2022). "HPV induces immune-checkpoint receptors such as CTLA-4 in the tumor microenvironment." (PMID 35632488, 2022). "Importantly, LS diet, on the other hand, reduced the systemic inflammatory irAE response while retaining the anti-tumor efficacy of anti-CTLA4 therapy." (PMID 35741331, 2022). "Similarly, a combination of mTOR kinase inhibitors with immune-checkpoint blockers such as anti-PD-1, anti-PD-L1, or anti-CTLA-4 significantly reduced MC38 or CT-26 tumor development." (PMID 36428613, 2022). "It has been demonstrated for OS metastatic patients that the combined anti-CTLA-4 program along with other immune factors with significance in this regard could result in improved anti-tumor activity and prompt recovery from the disease." (PMID 35145371, 2022). "One successful way to overcome tumor immune evasion has been the use of immune checkpoint inhibitors (ICIs), which increases the level of recognition of neoantigens by the immune system, thus inhibiting anergic signals, such as those driven by PD‐1 and CTLA‐4." (PMID 35284089, 2022). "Importantly, treatment with Anti-CTLA4 overcame this tumor resistance and promoted tumor regression." (PMID 35269518, 2022). "•Combination treatment with anti-CTLA-4 mAb and MUC1 mRNA nanovaccine could appear more effective than either nanovaccine or anti-CTLA-4 mAb alone at increasing level of apoptosis in tumor cells." (PMID 34875483, 2022). "Furthermore, in a B16 cancer model, combining anti-CTLA-4 and anti-PD-1 inhibitors improved the efficacy of a vaccine for tumor lysates, GM-CSF and CpG." (PMID 35337133, 2022). "In cocultures, each FRG and anti-CTLA-4 antibody significantly increased tumor cell apoptosis." (PMID 36618349, 2022). "However, gene expression profiling showed that CTLA-4 and PD-1 expression was significantly greater in tumours colonised by P. micra." (PMID 35301576, 2022). "An alternate possibility is that the function of anti-CTLA-4 in tumour therapy may be to induce the Fc-mediated destruction of Treg cells within tumour sites." (PMID 36119113, 2022). "Overexpression of immune checkpoint (CD96, PDL1, CTLA4) may lead to the depletion of anti-tumor immune cells in the microenvironment, which cannot play a good role in anti-tumor." (PMID 36744183, 2022). "Studies have reported that RT in combination with targeting CTLA-4 and/or PD-1/PD-L1 could provoke CTLs-mediated anti-tumor immunity." (PMID 34980128, 2022). "Further research discovered that inhibiting CTLA-4 could significantly suppress tumour growth in tumour model mice." (PMID 36700205, 2022). "In addition, the high tumor-infiltrating lymphocytes had a high-level expression of CTLA4 and PD-1, predicting a worse outcome in patients with ccRCC." (PMID 36010582, 2022). "The immune checkpoints such as CTLA-4 could downregulate the activation of cytotoxic T lymphocytes in the tumor microenvironment." (PMID 36468012, 2022). "Furthermore, inhibition of CTLA-4, another immune checkpoint, depletes regulatory T cells and thus reduces the degree of immunosuppression in the tumor microenvironment." (PMID 35280760, 2022). "CT-26 tumor highly responds to anti-CTLA-4 therapy whereas it is less sensitive to anti-PD-1." (PMID 35339889, 2022). "Blockade of CTLA4 promotes therapeutic response for T cell activation against tumor cells." (PMID 36685883, 2022). "Therefore, when radiotherapy is combined with immune checkpoint inhibitors (such as anti-PD-1 antibody, anti-PD-L1 antibody and anti-CTLA4 antibody), T cell activity directed against tumor cells can be increased." (PMID 36713375, 2022).